TRPV1 (transient receptor potential cation channel subfamily V member 1)
Diseases named in the same sentence as TRPV1 in open-access papers (continued):
Sharing a sentence is not in itself a finding about the gene and the disease.
acne (3 papers, 2021 to 2025). An inflammatory process of the sebaceous glands which is characterized by comedones, nodules, papules and/or pustules on the skin. "CBD also counteracts inflammation caused by Cutibacterium acnes—a bacterium associated with acne—by reducing cytokine expression via CB2R activation and TRPV-1 antagonism." (PMID 41008526, 2025). "This evidence suggests that targeting TRPV1 may be beneficial for acne and other sebaceous diseases, though its presence in sebaceous glands and response to high dose capsaicin needs to be considered when using TRPV1-targeted treatments in wounds." (PMID 34200205, 2021). "Although the primary focus was on acne, the mechanisms—such as suppression of IL-6, IL-8, and TNF-α via CB2 receptor activation and TRPV-1 modulation—are directly relevant to allergic contact dermatitis, where similar inflammatory pathways are involved." (PMID 41008526, 2025).
acute lymphoblastic leukemia (3 papers, 2020 to 2022). Leukemia with an acute onset, characterized by the presence of lymphoblasts in the bone marrow and the peripheral blood. "Furthermore, the endocannabinoid/endovanilloid system, composed of two G-protein coupled cannabinoid receptors (CB1 and CB2) and TRPV1, and their respective ligands and enzymes, is targeted in a novel therapeutic approach for T-cell acute lymphoblastic leukemia (T-ALL)." (PMID 32545311, 2020). "TRPV1, TRPV6 and TRPM2 contribute to the growth of cells derived from acute lymphoblastic leukemia (ALL)." (PMID 36330491, 2022).
allergic conjunctivitis (3 papers, 2021 to 2024). "Especially in allergic conjunctivitis, TRPV1 activates sensory neurons, causing pain and pruritus." (PMID 39195219, 2024). "Indeed, in a murine allergic conjunctivitis model, TRPV1 antagonists proved to be effective in ameliorating the clinical signs of ocular inflammation, although the observed beneficial effects in this work were at the level of T cells, not the corneal epithelium." (PMID 34360541, 2021). "They concluded that a TRPV1 antagonist rather than a TRPA1 antagonist may ameliorate allergic conjunctivitis by suppressing the Type 2 helper T cell cytokine response in draining lymph nodes." (PMID 39195219, 2024).
Allergy (3 papers, 2016 to 2022). An allergy is an immune response or reaction to substances that are usually not harmful. "Knockdown of the 1L-1R gene in highly TRPV1-expressing mice alleviated mechanical pain, while pretreatment with TRPV1 inhibitor in subcutaneously injected 1L-1β rats significantly alleviated heat pain allergy." (PMID 36430617, 2022). "Studies on seasonal AR report that more symptoms and pain are induced when stimulating TRPV1 intranasally with capsaicin during the allergy season compared with challenges outside of the season, suggesting sensitization to capsaicin during allergic inflammation." (PMID 33738577, 2021). "Obtaining an increased understanding of the role of TRPV1 in patients with AR might offer another option for the development of novel anti-inflammatory therapies for allergic diseases." (PMID 26700618, 2016). "Hence, it could be that TRPV1 expression depends on the presence of comorbid allergy." (PMID 33738577, 2021).
brain tumors (3 papers, 2020 to 2023). "Higher TRPV1 expression has also been reported in human primary brain tumors, and its expression correlates positively with the tumor grade." (PMID 35402237, 2022). "Therefore, the use of TRPV1 agonists may hold promise in the eradication of this particular brain tumor." (PMID 37569884, 2023).
channelopathies (3 papers, 2017 to 2025). "Several TRPV1 mutations have been associated with human channelopathies related to pain sensitivity or thermoregulation." (PMID 39998081, 2025). "Human TRPV1 subunit variants and associated channelopathies." (PMID 39998081, 2025). "Until recently, no channelopathy linked to TRPV1 variants was described in humans." (PMID 39998081, 2025). "On the other hand, both wild-type and mutant PACS2 (pGlu209Lys) interact with TRPV1 at different levels, implicating the importance of PACS2 in channelopathies." (PMID 35212819, 2022).
contact dermatitis (3 papers, 2017 to 2023). An inflammatory skin condition caused by direct contact between the skin and either an irritating substance or an allergen. "In addition, TRPV1 was found to be a critical mediator of persistent itch in a mouse model of squaric acid dibutylester-induced contact dermatitis (SADBE)." (PMID 36769042, 2023). "Our data provided the first evidence that both TRPA1 and TRPV1 channels are critical mediators of persistent itch in the mouse model of SADBE-induced contact dermatitis, which is independent of the lymphocyte-mediated immunity." (PMID 29081531, 2017).
cystinosis (3 papers, 2011 to 2016). Cystinosis is a metabolic disease characterized by an accumulation of cystine inside the lysosomes, causing damage in different organs and tissues, particularly in the kidneys and eyes. "We conclude that cystinosis patients homozygous for the 57-kb deletion exhibit a strong reduction of TRPV1 function, leading to sensory deficiencies akin to the phenotype of TRPV1-deficient mice." (PMID 27734949, 2016). "The most common genetic defect in a rare disease known as cystinosis involves a 57k base pair homozygous deletion on chromosome 17, that extends from the cystinosis gene into the early non-coding area for the TRPV1 gene (intron 2)." (PMID 27809268, 2016). "To evaluate the consequences of the 57-kb deletion on functional TRPV1 expression, we compared thermal, mechanical and chemical sensitivity of cystinosis patients with matched healthy controls." (PMID 27734949, 2016). "In this study, we provide evidence that homozygous deletion of the 57-kb fragment in cystinosis patients results in functional impairment of the TRPV1 receptor, as evidenced by a strongly reduced responsiveness to the selective TRPV1 activator capsaicin." (PMID 27734949, 2016). "To evaluate the potential influence of the 57-kb deletion on TRPV1 function, we compared chemical, mechanical and thermal sensitivity of cystinosis patients that were either homozygous or heterozygous for the deletion, with matched healthy controls." (PMID 27734949, 2016). "There are several, mostly anecdotal reports in the literature that cystinosis patients have a more frequent preference for spicy food or disturbances in thermoregulation than healthy subjects, but whether this is related to TRPV1 dysfunction is unknown." (PMID 27734949, 2016). "In conclusion, we demonstrate that cystinosis patients homozygous for the 57-kb deletion exhibit a significant reduction in capsaicin-induced dermal vasodilatation and pain, and thus provide a paradigm for life-long TRPV1 dysfunction in humans." (PMID 27734949, 2016). "About half of the cystinosis alleles in the Western populations are caused by a 57.2 kb deletion which extends from the tenth CTNS exon through the adjacent SHPK and first two exons of the TRPV1 (capsaicin receptor) gene." (PMID 22013525, 2011).
experimental autoimmune encephalomyelitis (3 papers, 2021 to 2026). An autoimmune demyelinating disease of the central nervous system that is produced experimentally in animals by the injection of homogenized brain or spinal cord in Freund's adjuvant. "In addition, TRPV1 deletion could alleviate mice experimental autoimmune encephalomyelitis (EAE) and reduce neuroinflammation by inhibiting NLRP3 inflammasome activation." (PMID 34907173, 2021).
fibrosis (3 papers, 2014 to 2022). the formation of excess fibrous connective tissue in an organ or tissue in a reparative or reactive process. "High expression of TRPV1 was observed in 80% (8/10) of the normal liver tissues, while only 40% (16/40) of the fibrosis specimens demonstrated a similar level of TRPV1 expression." (PMID 35909891, 2022). "Herein, we characterize the effects of TRPV1 on carbon tetrachloride- (CCl4-) induced mice, in vitro transforming growth factor-β- (TGF-β-) treated hepatic stellate cells (HSCs), and human fibrosis specimens." (PMID 35909891, 2022). "50% (3/6) of TRPM8 positive neurons expressed TLR5, 68.4% (13/19) of TRPV1 neurons expressed TLR5 and 62.5% (5/8) of TRPA1 expressed TLR5 in nodose/jugular ganglion in bleomycin induced fibrosis model." (PMID 29518161, 2018). "In DRG neurons, 41.2% (7/17) of TRPM8 positive neurons expressed TLR5, 59.1% (13/22) of TRPV1 neurons expressed TLR5 and 44.4% (4/9) of TRPA1 neurons expressed TLR5 in the bleomycin-induced fibrosis model." (PMID 29518161, 2018). "In the bleomycin-induced fibrosis model, 16.6% (1/6) of TRPM8 positive neurons expressed TLR2, 31.5% (6/19) of TRPV1 neurons expressed TLR2, and 12.5% (1/8) of TRPA1 expressed TLR2 in nodose/jugular ganglion." (PMID 29518161, 2018). "In the bleomycin-induced fibrosis model, 23.5% (4/17) of TRPM8 positive neurons expressed TLR2, 18.2% (4/22) of TRPV1 neurons expressed TLR2, and 44.4% (4/9) of TRPA1 neurons expressed TLR2 in the DRG." (PMID 29518161, 2018).
heart failure (3 papers, 2021 to 2026). Inability of the heart to pump blood at an adequate rate to meet tissue metabolic requirements. "In regards to potentially deleterious effects of TRPV1, various studies have associated its activation with increased hypertrophy and fibrosis contributing to the development of heart failure." (PMID 34867442, 2021). "TRPV1 also appears to play an important role in mediating the fibrotic response which is a critical factor involved in the structural remodeling of the heart that is associated with the development of heart failure (HF)." (PMID 34867442, 2021). "Resin toxin desensitizes cardiac afferent fibers by activating TRPV1 expression, thereby eliminating the sympathetic excitatory reflex of the heart, weakening cardiac remodeling, and alleviating cardiovascular dysfunction in rats with heart failure." (PMID 36045746, 2022).
hepatoblastoma (3 papers, 2017 to 2022). Hepatoblastoma (HB) is a malignant hepatic tumor and is the most common pediatric liver cancer. "Other than proliferation, TRPV1 has been associated with cell migration and in human hepatoblastoma HepG2 cells TRPV1-triggered Ca2+-influx promotes cell migration." (PMID 34356643, 2021). "A previous study reported that the hepatocyte growth factor promoted the migration of human hepatoblastoma cells by stimulating the activity of TRPV1, increasing intracellular calcium and triggering the signal cascade." (PMID 35558077, 2022). "However, in cancers such as hepatoblastoma, TRPV1 signals activate and stimulate migration of vascular endothelial cells, thus creating an opposing expectation that TRPV1 antagonists may have anticancer effects." (PMID 28081185, 2017).
Hypothermia (3 papers, 2015 to 2023). Reduced body temperature due to failed thermoregulation. "Hypothermia was abolished in mice pre-treated with resiniferatoxin to destroy or defunctionalize peripheral TRPV1-expressing terminals, but resistant to inhibition of cyclo-oxygenases." (PMID 26227887, 2015). "Hypothermia could be explained by the activation of TRPV1, and analgesia could be explained by the desensitization/downregulation of peripheral TRPV1 or by the activation of central TRPV1 in the descending pain pathway." (PMID 36077412, 2022).
intestinal motility disorder (3 papers, 2019 to 2025). "The release of neurotransmitters by stimulating TRPV1 can cause intestinal motility disorder, affect defecation, and form constipation." (PMID 30832248, 2019). "Because intestinal damage triggers intestinal motility disorder, TRPV1 expression in the small intestine is more pronounced during constipation." (PMID 40149894, 2025). "Activation of TRPV1 can trigger neurotransmitter (such as NO) release, resulting in intestinal motility disorder." (PMID 34136194, 2021).
myeloma (3 papers, 2020 to 2025). "Western blotting was first performed on THP-1 cells and U266B1 myeloma cells that express TRPV1 monomer (~ 95 kDa) and U266B1 that also expresses a dimer." (PMID 35477804, 2022). "To determine the potential of TRPV1 inhibition in myeloma, we exposed a panel of MM cell lines and primary CD138 + MM cells to AMG9810, a specific inhibitor of TRPV1, for 48 h." (PMID 33239060, 2020). "Overexpression of TRPV1 was observed in THP-1 (acute monocytic leukemia) and U266B1 (multiple myeloma, MM), but not U937 (histiocytic lymphoma) compared to healthy PBMC." (PMID 35477804, 2022).
non-small cell lung carcinoma (3 papers, 2022 to 2023). A group of at least three distinct histological types of lung cancer, including non-small cell squamous cell carcinoma, adenocarcinoma, and large cell carcinoma. "Another interventional study (NCT04923412) aims to investigate TRPA1 and TRPV1 expression in non-small cell lung cancer (NSCLC) patients before and after surgery to quantitatively measure injuries of the vagus nerve during mediastinal lymph node dissection." (PMID 37892239, 2023). "Moreover, the gene inactive (iav), which is an orthologue of TRPV1 (transient receptor potential cation channel subfamily V member 1) in humans in response to capsaicin and has been reported to promote chemoresistance in non-small-cell lung cancer." (PMID 37686177, 2023).
papilloma (3 papers, 2012 to 2024). A benign epithelial neoplasm that projects above the surrounding epithelial surface and consists of villous or arborescent outgrowths of fibrovascular stroma. "In TRPV1-null mice, increased papilloma incidence and multiplicity were reported." (PMID 32887395, 2020). "Thus, TRPV1 has been found to exhibit tumor suppressive activity on skin carcinogenesis in mice because of its ability to down-regulate EGFR expression; conversely, loss of TRPV1 expression resulted in marked increase in papilloma development." (PMID 22523714, 2012). "In a 26-week dermal oncogenicity study, topical capsaicin (the prototypical TRPV1 agonist) did not increase papilloma formation in the mouse skin treated by the tumor promoter, 12-O-tetradecanoylphorbol-13-acetate (TPA)." (PMID 32887395, 2020). "In addition, mice with pharmacologically inactivated (desensitized by resiniferatoxin) TRPV1 showed no increase in papilloma growth in the two-stage skin carcinogenesis model (Blumberg and Szallasi, unpublished observations)." (PMID 32887395, 2020). "In addition, why do we not see increased papilloma formation in mice whose TRPV1 were ablated by resiniferatoxin pretreatment?" (PMID 32887395, 2020).
Psoriasiform dermatitis (3 papers, 2021 to 2022). A skin abnormality characterized by redness and irritation, with thick, red skin that displays flaky, silver-white patches (scales). "In the current study, the drug absorption through the psoriatic epidermal barrier was tested as a function of time during the development of IMQ-induced psoriasiform dermatitis in wild type, TRPV1 KO and TRPA1 KO mice." (PMID 35457056, 2022). "TRPV1 function seems to be essential for the development of psoriasiform dermatitis—therefore, blocking TRPV1 leads to severely impaired inflammation in the IMQ model." (PMID 35457056, 2022). "In the development of IMQ-induced psoriasiform dermatitis, intact TRPV1-positive neurons are essential for the initial Type17-mediated inflammation." (PMID 34745116, 2021). "In the current study, we provide the evidence of the modulation of IL-23 expression by TRPV1-positive sensory neurons via CGRP that affects their central role in the onset of IMQ-induced psoriasiform dermatitis." (PMID 34745116, 2021).
retinoblastoma (3 papers, 2015 to 2025). A malignant tumor that originates in the nuclear layer of the retina. "Another study revealed TRPV1, TRPM8 and TRPA1 gene expression in retinoblastoma cells." (PMID 26605361, 2015). "TRPV1, TRPM8 and TRPA1 are expressed in retinal tumour cells (retinoblastoma)." (PMID 26605361, 2015).
skin aging (3 papers, 2017 to 2023). The gradual irreversible changes in structure of skin that occur as a result of the passage of time.. "Collectively, the various downstream signaling pathways of TRPV1/Ca2+ are involved in UV-induced skin aging." (PMID 36874007, 2023). "On the other hand, the upturning effect of aging on the anti-inflammatory function of TRPV1 denoted its impaired role in the suppression of tumor necrosis factor α in old mice, and of numerous cytokines involved in skin aging." (PMID 37108704, 2023). "Therefore, the development of TRPV1-specific, non-toxic inhibitors may be an effective strategy for the prevention of skin aging." (PMID 36874007, 2023).
small fiber neuropathy (3 papers, 2018 to 2023). "Amongst the strongest TRPV1 sensitizers were proteasome inhibitors, a class that includes bortezomib, a chemotherapeutic agent that causes small fiber neuropathy in 30–50% of patients." (PMID 38052846, 2023). "The role of membrane integrity in the PAP-mediated antinociceptive effect in small-fiber neuropathy remains unclear, especially with respect to whether TRPV1 and PAP are colocalized in the same microdomain which is responsible for PAP-mediated antinociception." (PMID 30578250, 2019).
steatosis (3 papers, 2016 to 2025). Increased lipid within the cytoplasm of cells. "We confirmed TRPV1 expression in the liver and demonstrated that CAP activates hepatic TRPV1, thereby preventing steatosis, improving insulin sensitivity, reducing inflammation, and enhancing fatty acid oxidation." (PMID 40864772, 2025). "While CAP treatment failed to prevent fat accumulation in TRPV1−/− mice, it effectively protected WT mice from steatosis." (PMID 40864772, 2025).
synovitis (3 papers, 2016 to 2022). Inflammation of a synovial membrane. "In our previous studies, we identified TRPV1 channels as a therapeutic target to inhibit synovitis as well as OA progression." (PMID 36552524, 2022). "In conclusion, we found that TRPV1 is a novel therapeutic target for inhibiting M1 macrophage polarization and decreasing synovitis to attenuate OA progression, unveiling a new mechanism for the topical administration of CPS for the treatment of OA." (PMID 34006826, 2021). "The results demonstrated that targeting TRPV1 is a potential therapeutic approach to prevent M1 macrophage polarization to reduce synovitis and slow OA progression." (PMID 34006826, 2021). "However, whether TRPV1 can regulate M1 macrophage polarization and the role of TRPV1 in OA synovitis remain unknown." (PMID 34006826, 2021). "Beyond regulating pain responses, we showed that TRPV1 was involved in the regulation of macrophage polarization as it was highly localized to M1 macrophage, and the increase of the infiltrated M1 macrophage was highly correlated with synovitis and subsequent severity of OA19." (PMID 34006826, 2021).